MITF (melanocyte inducing transcription factor)
Diseases named in the same sentence as MITF in open-access papers (continued):
Sharing a sentence is not in itself a finding about the gene and the disease.
psoriasis (2 papers, 2018 to 2021). An autoimmune condition characterized by red, well-delineated plaques with silvery scales that are usually on the extensor surfaces and scalp. "In psoriasis lesional skin, MITF mRNA expression was 3.2-fold lower (p < 0.001) and in non-involved skin it was 1.9-fold lower (p < 0.05) compared with the skin of healthy control subjects." (PMID 34884858, 2021). "Likewise, another inflammatory cytokine associated with psoriasis, interferon gamma, has been shown to suppress CREB, MITF, p38 MAPK and melanogenesis." (PMID 34884858, 2021). "This may result from elevated proinflammatory cytokines in psoriasis-TNF, IL-17, IL-1 and IL-6, which are known to inhibit melanogenesis and specifically PKA, MITF, TYR and DCT." (PMID 34884858, 2021). "In psoriasis lesional skin, a 1.7-fold decrease (p < 0.01) in MITF mRNA expression was established when compared with psoriasis non-lesional skin." (PMID 34884858, 2021). "In psoriasis, melanocytes are elevated; however, MITF expression was noted to be comparable to controls." (PMID 30148172, 2018). "In psoriasis uninvolved skin, positive correlations were found between the expression levels of CREB1 and LEF1 (r = 0.66, p < 0.05), USF1 and PNOC (r = 0.81, p < 0.05), MITF and ATRN (r = 0.58, p < 0.05), MITF and NURR1 (r = 0.56, p < 0.05) and MITF and MAPK14 (r = 0.75, p < 0.01)." (PMID 34884858, 2021).
pulmonary hypertension (2 papers, 2014 to 2016). Increased pressure within the pulmonary circulation due to lung or heart disorder. "MITF stimulates the transcription of HIF1A, which contributes to pulmonary hypertension." (PMID 28002425, 2016). "Many genes are functionally related to high-altitude physiology, such as angiogenesis (RGCC), pulmonary hypertension remodeling (PLA2G12A), oxygen intake (C9ORF3), neural response (GRID1 and GRIN2B), melanin synthesis (MITF, PDGFRB and PIK3R3) and heart development (FOXS1, GAA and MYLK2)." (PMID 25270331, 2014).
schwannoma (2 papers, 2022 to 2025). A benign, usually encapsulated slow growing tumor composed of Schwann cells. "In agreement with this hypothesis, constitutive activation of β-catenin in Schwannoma cells led to FOXD3 repression, whereas MITF silencing upregulated FOXD3 expression in melanoma cell lines." (PMID 34878101, 2022).
systemic mastocytosis (2 papers, 2023). Systemic mastocytosis (SM) comprises a heterogeneous group of rare acquired and chronic hematological malignancies that are related to an abnormal proliferation of mast cells in tissue, including bone marrow, with or without skin involvement. "The microphthalmia-associated transcription factor (MITF) is highly expressed in bone marrow biopsies from 9 of 10 patients with systemic mastocytosis and activating KIT mutations." (PMID 36834926, 2023). "Moreover, MITF is highly expressed in bone marrow biopsies from patients with systemic mastocytosis and activating KIT mutations." (PMID 37234172, 2023).
thyroid cancer (2 papers, 2016 to 2023). "In addition to well-known BRAF, RAS, and RET mutations, NGS technology facilitated detection of new somatic alterations in thyroid cancer such as MITF, MDM2, JAK3, FLI1, IDH1 etc., all in which the significance of thyroid cancer has not been delineated yet." (PMID 27871285, 2016).
uterine carcinosarcoma (2 papers, 2019 to 2020). A usually aggressive malignant neoplasm arising from the uterine corpus and less often the cervix. "Interestingly, uterine carcinosarcomas (mixed Mullerian tumors) have been reported to exhibit melanocytic differentiation, and increased MITF expression." (PMID 33051548, 2020).
actinic keratosis (1 paper, 2025). A precancerous lesion of the skin composed of atypical keratinocytes. "Regarding differential diagnosis, MITF can be used to differentiate actinic keratosis with melanocyte hyperplasia from melanoma in situ with greater efficacy than SOX10." (PMID 40507250, 2025). "MITF could provide important information when faced with the differential diagnosis of actinic keratosis with melanocyte hyperplasia and melanoma in situ, while p16 could help the diagnosis of a primary tumour and provides additional prognostic information." (PMID 40507250, 2025).
amelanotic melanoma (1 paper, 2023). A melanoma characterized by the complete absence of melanin pigment in the melanoma cells. "The human amelanotic melanoma A375 cells were also reported to express a very low level of MITF and its target gene TYR." (PMID 38020918, 2023).
angiosarcoma (1 paper, 2021). A malignant tumor arising from the endothelial cells of the blood vessels. "The tumor cells were negative for desmin, HHF35, HMB45, Melan A, MITF, c-kit, DOG1, cytokeratin AE1/AE3, h-caldesmon, STAT6, CD68, CD31, Factor 8, and ERG, making diagnoses of PEComa, GIST, SFT, and angiosarcoma unlikely." (PMID 34797454, 2021).
Areflexia (1 paper, 2025). Absence of neurologic reflexes such as the knee-jerk reaction. "In patients with MITF pathogenic variations, vestibular function was normal in all but one, who exhibited total vestibular loss (areflexia)." (PMID 40868272, 2025). "Additionally, it is worth noting that one patient with a MITF pathogenic variant exhibited complete vestibular loss (areflexia), demonstrating that severe vestibular involvement is not exclusive to WS cases with SOX10 pathogenic variants." (PMID 40868272, 2025).
basophil leukemia (1 paper, 2022). "In the present study, we further explored the role played by mitochondrial MITF in mast cell exocytosis using rat basophil leukemia cells [RBL], as well as mouse bone marrow-derived mast cells (BMMCs)." (PMID 35159398, 2022).
bone marrow failure (1 paper, 2021). "The pharmacological modulation of the MiTF expression could be useful for care in several pathological setting, as bone marrow failure and bone abnormalities." (PMID 33441180, 2021).
bone metastasis (1 paper, 2021). Transfer of a neoplasm from its primary site to bones. "Studies have shown that factor MITF can promote and survive osteoclast precursors, greatly enhancing the incidence of bone metastasis pain." (PMID 33494823, 2021).
cervical tumors (1 paper, 2021). "ZNF382 was firstly identified as a direct repressor for several oncogenes (i.e., MYC, MITF, HMGA2, and CDK6) across distinct types of cancers, including lung, esophageal, colon, stomach, breast, and cervical tumors." (PMID 34638319, 2021).
craniopharyngioma (1 paper, 2019). A benign, partly cystic, epithelial tumor of the sellar region, presumably derived from Rathke pouch epithelium.
diffuse large B-cell lymphoma (1 paper, 2024). "Indeed, MITF expression has been observed in patients with diffuse large B-cell lymphoma (DLBCL), and it has been reported that high MITF expression in macrophages is associated with poor overall survival." (PMID 38351314, 2024).
dwarfism (1 paper, 2022). "Other regions included novel candidate genes that might contribute to the phenotypic variation among the analyzed breeds, including genes for pigmentation-related traits (EDNRA, EDNRB, MITF and OCA2) and body size, with a strong candidate for dwarfism in rabbit (COL2A1)." (PMID 35062866, 2022).
epilepsy (1 paper, 2016). A brain disorder characterized by episodes of abnormally increased neuronal discharge resulting in transient episodes of sensory or motor neurological dysfunction, or psychic dysfunction. "Several genes which have been linked to cell death in cancer, epilepsy, or psychological disorders but not yet associated with brain injury, including CSNK2A1, ELAVL1, MITF, and SMARCA4, were also identified which may provide additional therapeutic targets for prevention of cell death following TBI." (PMID 26912237, 2016).
Epithelioid Malignant Peripheral Nerve Sheath Tumor (1 paper, 2021). A rare variant of malignant peripheral nerve sheath tumor composed predominantly or exclusively of epithelioid cells. "Epithelioid schwannoma and epithelioid malignant peripheral nerve sheath tumor (MPNST) lie in the differential as well, but they are consistently negative for melanocytic markers including MITF, and a subset of them shows loss of INI1 expression." (PMID 34943200, 2021).
fatty acid metabolic disorders (1 paper, 2025). "Furthermore, fatty acid metabolic disorders induced by MITF have also been verified in lymph node (LN) metastasis, though these results are mainly from AM metastatic lesions." (PMID 40866912, 2025).
hepatitis C (1 paper, 2017). "MITF was upregulated in eight cases (33%), and etiologies were: chronic HBV (n=2), hepatitis C (n=3), and NASH (n=1); two hepatitis C and one HBV patients had established liver cirrhosis." (PMID 29383183, 2017).
mastitis (1 paper, 2018). Inflammation of breast tissue during lactation or postpartum due to an obstructed duct or infection. "In addition, in this study, predicted activation status of transcription regulators showed the activation of STAT1, MITF, and various interferon regulatory factors in mastitis milk." (PMID 30271395, 2018).
melanocytic neoplasm (1 paper, 2025). "These include Melan-A, HMB-45, tyrosinase, and MITF, which are typically specific to melanocytic neoplasms." (PMID 40598734, 2025).
melanocytic nevus (1 paper, 2023). A neoplasm composed of melanocytes that usually appears as a dark spot on the skin. "In the nests of melanocytic nevus, co-staining of GREB1 and MITF and some scattered brown melanin pigments were observed." (PMID 37658191, 2023).
metanephric adenoma (1 paper, 2015). A benign, well-circumscribed renal cortical neoplasm affecting females more often than males. "Napsin A was immunoreactive in 2 of 2 (100%) acquired cystic disease associated RCC, 3 of 3 (100%) metanephric adenoma, 0 of 1 (0%) mucinous tubular and spindle cell carcinoma, and 0/1 (0%) TFE/MITF RCC." (PMID 25889632, 2015).
oral cancer (1 paper, 2024). "CSE1L could also promotes the proliferative and migratory abilities in oral cancer by positively regulating MITF and activating the Akt/mTOR pathway." (PMID 39430746, 2024).
Osteopenia (1 paper, 2015). Osteopenia is a term to define bone density that is not normal but also not as low as osteoporosis. "The importance of MITF as a regulator of osteoclasts has long been appreciated, starting with the mutant mouse microphthalmia (Mitfmi), which exhibits severe osteopenia among other phenotypes." (PMID 25875108, 2015).
pancreatic ductal adenocarcinoma (1 paper, 2021). An infiltrating adenocarcinoma that arises from the epithelial cells of the pancreas. "In pancreatic ductal adenocarcinoma, MITF has been identified as a master regulator of metabolic reprogramming via control of the autophagy-lysosome system." (PMID 34208068, 2021).
pigmentary glaucoma (1 paper, 2021). Pigmentary glaucoma is a type of secondary open-angle glaucoma characterized by heavy homogenous pigmentation of the trabecular meshwork, iris transillumination defects, and pigment along the corneal endothelium (Krukenberg spindle). "GPNMB also localizes to melanosomes, is transcriptionally regulated by the Melanocyte-Inducing Transcription Factor (MITF) and, when mutated, can lead to hypopigmented lesions and pigmentary glaucoma in mice." (PMID 34207849, 2021).
proliferative diabetic retinopathy (1 paper, 2025). Advanced retinopathy due to diabetes mellitus characterized by the formation of new vessels in the retina. "MITF, a master regulator of the RPE differentiation and homeostasis, was footprinted on VEGFB proximal promoter (−2, TSS) and VEGFA, with major clinical relevance in neovascular AMD and proliferative diabetic retinopathy." (PMID 40565279, 2025).
prostate tumor (1 paper, 2018). "Following this rationale, we identify Microphthalmia-associated transcription factor (MITF) as a prostate tumor suppressor among a subset of transcription factors." (PMID 30310055, 2018). "In the present study, by combining an exhaustive interrogation of seven publically available PCa databases with refined empirical assays, we have identified MITF as a prostate tumor suppressor." (PMID 30310055, 2018).
rectal adenocarcinoma (1 paper, 2025). "Among the lpVUSs, MITF was present in one patient with CRC, more specifically rectal adenocarcinoma." (PMID 40627234, 2025).
renal oncocytoma (1 paper, 2022). "This would include renal oncocytoma, eosinophilic variant of chromophobe RCC, succinate dehydrogenase (SDH)-deficient RCC, MiTF translocation RCC (particularly TFEB), and epithelioid angiomyolipoma (AML)." (PMID 35203531, 2022).
retinal diseases (1 paper, 2024). "Exploring the role of MITF in pathways associated with retinal diseases is crucial due to its impact on a wide array of biological functions in RPE cells, offering potential for therapeutic advancements." (PMID 39457382, 2024).
rhabdoid tumor (1 paper, 2024). An aggressive malignant embryonal neoplasm usually occurring during childhood. "Interestingly, even though rhabdoid tumors have been suggested to potentially derive from neural crest cells similar to melanocytes, neither rhabdoid cell lines from DepMap nor ATRT cell lines from our study were dependent on SOX10 or MITF." (PMID 39617889, 2024).
Sensorineural hearing impairment (1 paper, 2022). A type of hearing impairment in one or both ears related to an abnormal functionality of the cochlear nerve. "WS2A is caused by the mutation of microphthalmia-associated transcription factor (MITF), an essential regulator for melanocyte lineage development, and is characterized by varying degrees of pigmentation abnormalities and sensorineural hearing impairment." (PMID 35805166, 2022).
sensorineural hearing loss (1 paper, 2022). "Studies have shown that variants in SOX10 and MITF were identified in some nonsyndromic sensorineural hearing loss (NSHL) cases, which implies the clinical and genetic heterogeneity of this syndrome." (PMID 36329483, 2022).
Sepsis (1 paper, 2023). Sepsis is defined as life-threatening organ dysfunction caused by a dysregulated host response to infection. "The evaluation of ROS levels in lung tissue also showed that lung tissue with a high expression of MITF or GAS5 showed lower ROS levels under sepsis, while lung tissue overexpressing miR-23 displayed noticeably higher ROS levels." (PMID 37509452, 2023). "In summary, the protective effect of GAS5 in sepsis is mainly the result of the synergistic effect of the target gene transcribed by MITF." (PMID 37509452, 2023). "The high expression of MITF or GAS5 correlated with relatively lower autophagy intensity, attributable to the antioxidant effect of MITF-transcribed Nrf2, which in turn contributes to the maintenance of autophagic flux during sepsis." (PMID 37509452, 2023).
serous carcinoma (1 paper, 2020). "Immunoblotting analysis of high-grade serous carcinoma, the most common histological type of OvCa that accounts for approximately 70% of cases, found that all samples expressed MITF, although the expression was variable." (PMID 33371469, 2020).
skin aging (1 paper, 2021). The gradual irreversible changes in structure of skin that occur as a result of the passage of time.. "In the next core pathway of both middle-aged and elderly skin aging, the ligand KITLG promotes melanin synthesis, DNA damage, and inhibits cell-cycle arrest by modulating TFs AR and MITF via signaling transduction proteins FAM83H, HSPB1, PAX3, ATF5, and H2AFB2." (PMID 34073305, 2021). "TF AR downregulated not only target gene TYR through triggering TF MITF to promote melanin synthesis, but also target gene CDH1, which was modified by phosphorylation, to promote cell-cycle, apoptosis and DNA damage in both middle-aged and elderly skin aging." (PMID 34073305, 2021).
skin hyperpigmentation (1 paper, 2021). "Therefore, the downregulation of the transcriptional activity or protein stability of MITF through modulating CREB and MAPK signaling pathways in melanocytes is a potentially valuable strategy to control skin hyperpigmentation." (PMID 33917957, 2021). "Therefore, the downregulated MITF expressions and stability through modulating MAPK signaling in melanocytes are promising targets for the development of cosmeceuticals or therapeutics for skin hyperpigmentation." (PMID 33917957, 2021).
spindle cell carcinoma (1 paper, 2015). "Approximately one-half (47.4%) of the recently described entity clear cell papillary RCC also labeled for Napsin A. Immunoreactivity for napsin A was not seen in mucinous tubular and spindle cell carcinoma or TFE/MITF RCC." (PMID 25889632, 2015). "Expression of napsin A was not seen in mucinous tubular and spindle cell carcinoma (0/1, 0.0%), TFE/MITF RCC 0/1, 0.0%), and urothelial carcinoma (0/6, 0.0%)." (PMID 25889632, 2015).
ZIKV infection (1 paper, 2023). "We observed that MITF-positive RPE cell layer and internal VSX2 expressing neural retinal cells are permissive to ZIKV infection, suggesting a broader ZIKV tropism, which can result in retinal abnormalities in a developing eye." (PMID 36680182, 2023).